BDNF (brain derived neurotrophic factor)
Diseases named in the same sentence as BDNF in open-access papers (continued):
Sharing a sentence is not in itself a finding about the gene and the disease.
neurological disorders (continued). "Corticosterone has been shown to negatively regulate BDNF expression in the hippocampus and lowering corticosterone levels restores BDNF/TrkB expression which may find implications in neurological disorders characterised by seizures." (PMID 23670594, 2013). "Efforts to develop pharmacological and molecular genetic methods for activating BDNF-signaling pathways may result in novel therapeutic treatments for a range of metabolic and neurological disorders." (PMID 22548651, 2012). "Essentially, they could be mediating a differential biphasic time pattern expression of the BDNF/trkB receptor complex, which precedes DA cell death in SN and the clinical symptoms of this neurological disease." (PMID 22720191, 2012). "Thus, investigating the conditions required for proper trafficking and release of BDNF is an essential step toward understanding and potentially improving these neurological disorders." (PMID 22720171, 2012). "The preclinical evidence strongly supports the idea that BDNF might be useful as a therapeutic agent for a variety of neurological disorders." (PMID 20644624, 2010). "Hence, deoxygedunin imitates BDNF's biological activities through activating TrkB, providing a powerful therapeutic tool for treatment of various neurological diseases." (PMID 20644624, 2010). "Therefore, microporation-based successful genetic modification of hUCB-MSCs with BDNF makes them potential candidates for the treatment of neurological diseases." (PMID 20462460, 2010). "Therefore, all of these animal models strongly support the notion that deoxygedunin mimics BDNF in vitro and in vivo and reveal remarkably therapeutic activities in various neurological diseases." (PMID 20644624, 2010). "Thus, BDNF is pathological in many psychiatric, neurodegenerative and other neurological diseases." (PMID 38752280, 2024). "Therefore, targeting BDNF/TrkB signaling to restore neuroplasticity mechanisms at corticostriatal synapses could open potential therapeutic avenues for treating these neurological diseases." (PMID 39200225, 2024). "Therefore, regulating BDNF signalling could treat a variety of psychiatric and neurological disorders." (PMID 37909847, 2023). "Hypoxia and inflammation may lead to BDNF/TrkB dysregulation and neurological disorders." (PMID 35112804, 2022). "Therefore, the augmentation of BDNF is of interest as a mechanism by which these interventions may afford protection to people suffering from neurological diseases." (PMID 36501116, 2022). "Furthermore, it has been reported that lysoPC can increase levels of the brain-derived neurotrophic factor and improve cognition and, thus, may be used as a potential treatment for neurological diseases." (PMID 35684108, 2022). "Thus, the BDNF/Pro-BDNF ratio appears to be fundamental, and impairment of this balance may play a major role in the development of nervous system diseases." (PMID 35625004, 2022). "However, whether the BDNF-ERK signaling is involved in the psychiatric comorbidities of neurological diseases is still unclear." (PMID 34489702, 2021). "Thus, maintaining a certain BDNF level in the brain could suppress the onset and progression of neurological disorders." (PMID 34977362, 2021). "Therefore, enhancing Bdnf transcription in these pathological conditions may result in therapeutic effects, and agents that can induce BDNF expression in neurons may be candidate therapeutic drugs for neurological diseases." (PMID 34977362, 2021). "Acupuncture treats nervous system diseases by increasing the brain-derived neurotrophic factor level and involving multiple signal pathways, which may be related to amino acid metabolism and inflammatory pathways, especially the toll-like receptor signaling pathway." (PMID 32051687, 2020). "Thus in the context of LNS, BDNF may be amenable to therapeutic modulation as suggested for other neurological disorders." (PMID 24804781, 2014).
neurological disorders (continued). "In addition to the role of BDNF in neurological disorders, recent studies reported that peripheral injection of BDNF exerts hypophagic and hypoglycemic effects on obese hyperglycemic animals but not on normal animals, pointing to antiobesity and antidiabetic effects." (PMID 25587547, 2014). "BDNF expression has also been increasingly tied to promoter DNA methylation in various models of neurological disease, indicating that even under normal developmental conditions, BDNF promoter methylation may be significantly responsible for neurotrophic levels." (PMID 25206361, 2014). "Therefore, if hUCB-MSCs could be successfully modified with BDNF gene by microporation, it would be a valuable cell source for the treatment of neurological disease." (PMID 20462460, 2010). "Promoting BDNF and GDNF release is a promising therapeutic strategy for the treatment of neurological disorders." (PMID 40904189, 2025). "These polymers interacted with brain-derived neurotrophic factor (BDNF) through electrostatic attractions and hydrogen bonding, leading to the formation of a novel PIC with the potential for therapeutic activity in neurological diseases." (PMID 39000726, 2024). "BDNF has a promising potential as a treatment for central nervous system diseases such as brain disease and SCI; however, its application for neurological diseases is limited." (PMID 38886817, 2024). "In addition, we also identified decreased levels of BDNF, in SOD1-ALS MNs, which is a key growth factor required for the cell growth/neuronal survival in the brain, whereas reduced expression has been associated with neuronal dysfunction and death in several neurological disorders including ALS." (PMID 39588282, 2024). "Concurrently, BDNF, as one of the downstream targets of CREB, plays a vital role in neurological diseases." (PMID 35401106, 2022). "NSCs overexpressing neurotrophins (i.e., GDNF, BDNF, NT-3, and NGF) display improved survival and increased proliferative and neuroprotective properties in different neurological disease models." (PMID 32354178, 2020). "Other authors clearly indicated the important role of the BDNF/CaMK/CREB signaling pathway in neuronal activation, proper synaptic plasticity, and further neurological disorders." (PMID 33238370, 2020). "Moreover, the results presented here give further support to the idea that a functional coupling between NMDA receptors and BDNF/trkB signaling may be important for the maintenance of the dopaminergic phenotype in SNc during the presymptomatic stages of this neurological disease." (PMID 22720191, 2012). "Taken together, promotion of BDNF and GDNF release are recognized to hold a promising therapeutic strategy for the treatment of neurological disorders." (PMID 23304227, 2012). "Recent evidence has demonstrated that natural compounds which increase the endogenous expression of BDNF and/or TrkB, as well as BDNF mimetic compounds that are small molecules passing the blood–brain barrier (BBB), look promising to treat brain diseases including mental and neurological disorders." (PMID 40005159, 2025). "In neurological disorders, bioactive factors such as nerve growth factor (NGF) promote stem cell differentiation into neural-like cells, while brain-derived neurotrophic factor (BDNF) and glial cell-derived neurotrophic factor (GDNF) enhance neurite outgrowth and Schwann cell function." (PMID 40710251, 2025). "BDNF and NGF modulation are vital markers for treating or preventing neurologic diseases." (PMID 39628974, 2024). "Neurological diseases in the brain are largely influenced by the AKT/CREB/BDNF signaling pathway, which is involved in protein kinase B/CAMP response element binding protein/brain-derived neurotrophic factor." (PMID 38946910, 2024). "In conclusion, a single bout of endurance exercise significantly elevates BDNF levels in humans without neurological disorders, regardless of age." (PMID 36671818, 2023).
neurological disorders (continued). "Although there is an emerging understanding of the pathophysiology of acupuncture in treating neurological disorders, the mechanisms of acupuncture treatment and the BDNF signaling pathways have not been elucidated." (PMID 37780709, 2023). "Since BDNF is a negatively charged protein, it does not pass through the blood-brain barrier, making therapeutic strategies a challenge for the treatment of neurological diseases." (PMID 35721318, 2022). "Brain-derived neurotrophic factor (BDNF) is critical to the healthy development and function of the brain, and dysregulated levels of the neurotrophin are found in numerous neurological disorders." (PMID 35354099, 2022). "Neurotrophins (NGF, BDNF, NT3, and NT4) and bioactive compounds that activate neurotrophin receptors may be able to treat neurodegenerative and neurological diseases." (PMID 36846103, 2022). "The neurological disorder of the interaction between CD4 and BDNF has also been reported." (PMID 37786738, 2022). "This increases the potential therapeutic use of BDNF for the treatment of neurological diseases and enhances its potential administration through non-invasive intranasal pathways as a brain delivery strategy for BDNF and other neurotrophic factors." (PMID 35194435, 2021). "Despite its importance in brain function and neurological diseases, BDNF has been difficult to study because of the lack of sensitive methods to detect it at low levels." (PMID 27640722, 2016). "Moreover, the relevance of oxidative stress and the potential benefit of such factors as BDNF, GDNF and IGF-1 in multiple other neurological diseases (e.g. ALS and Huntingdon's chorea) indicate obvious potential applications of GDAsBMP in other settings." (PMID 24477866, 2014). "The secretome of MSC culture with combined hyperexpression of BDNF and uPA and suppressed expression of Von Hippel–Lindau tumor suppressor even without additional concentration reduced the severity of neurological disorders and decreased brain lesion volume in the ICH model." (PMID 40724947, 2025). "Exercise is proposed as a non-pharmacological strategy to enhance BDNF; however, findings across neurological and non-neurological disorders remain inconsistent, and the influence of exercise type or dose-related parameters remains unclear." (PMID 41594760, 2025). "Additionally, some research has suggested that the levels of BDNF may be subject to regulation by HMGB1, particularly in neurological disorders and inflammatory processes." (PMID 38982490, 2024). "However, there was no apparent correlation between plasma BDNF levels and other neurological disorders or related subtypes." (PMID 38707431, 2024). "Meanwhile, the expression of BDNF and its receptors has also been shown to be modulated in non‐neurological diseases, such as cancer and cardiovascular diseases, thereby influencing disease progression, with these effects being particularly significant in cancer." (PMID 39648800, 2024). "Although DHF is reported to work as BDNF mimic by activating TrkB and when used, it has neuroprotective effects on relevant neurological diseases, others reported that they were not able to detect DHF ability to bind and activate TrkB protein in in vitro settings." (PMID 34855884, 2021). "Brain-derived neurotrophic factor (BDNF)-overexpressing hNSPCs, glial cell line-derived neurotrophic factor (GDNF)-overexpressing hNSPCs, and insulin-like growth factor 1 (IGF-1)-overexpressing hNSPCs have all been shown significant therapeutic effects on neurological disorders." (PMID 34827135, 2021). "Similarly, NSCs stable-expressing neurotrophies, such as glial cell-derived neurotrophic factor (GDNF), brain-derived neurotrophic factor (BDNF), and NGF, exhibited remarkably improved proliferation, survival, and functional recovery in different neurologic disease animal models." (PMID 34135002, 2021).
neurological disorders (continued). "However, due to space limitations, this review will not address the current knowledge regarding BDNF signaling in the pathophysiology and therapy of neurological diseases." (PMID 32537724, 2020). "Furthermore, BDNF immunoreactivity has been shown to increase with conditions such as hypoxia or neuroinflammation, which are part of the pathogenesis of different neurological diseases, not fully studied in the context of RTT brain." (PMID 32974336, 2020).
cancer (305 papers, 2009 to 2026). A tumor composed of atypical neoplastic, often pleomorphic cells that invade other tissues. "For instance, low serum BDNF levels have been associated with worsening fatigue during external beam radiation therapy in cancer patients and adults with osteoarthritis." (PMID 40002745, 2025). "Epigenetic ageing measures influenced by cancer treatment had expected associations BDNF levels, with accelerated ageing significantly associated with decreasing BDNF levels." (PMID 41403898, 2025). "Circulating BDNF levels have been shown to decline over the course of chemotherapy, and lower levels were found to be associated with worse cognitive outcomes among cancer patients in several studies." (PMID 40597835, 2025). "Several studies have found a positive association between peripheral BDNF level and cognition in cancer patients more generally." (PMID 39863251, 2025). "First, we evaluated associations of accelerated epigenetic ageing with cancer status and treatment, circulating BDNF levels, and cognitive function." (PMID 41403898, 2025). "PhenoAge and GrimAge demonstrated significant age acceleration relative to non-cancer controls and worsening cognitive function symptoms, with accelerated GrimAge associated with decreasing BDNF levels." (PMID 41403898, 2025). "Our group is investigating the relationships between the BDNF rs6265 polymorphism and PN symptoms among male and female cancer survivors." (PMID 37462904, 2024). "The relationships of BDNF rs6265 polymorphism with cancer-related fatigue and neuropathic pain were also confirmed by multivariable rank-based regression." (PMID 37462904, 2024). "The BDNF/TrkB signaling pathway is closely linked to the development of cancer and cardiovascular diseases." (PMID 39648800, 2024). "Neuropathic pain score was associated with the BDNF rs6265 Met/Met genotype (slope = 9.30, p < 0.001), years since cancer diagnosis (slope = -0.08, p = 0.02), and having a master’s/PhD (slope = -1.00, p = 0.01)." (PMID 37462904, 2024). "Our findings advance the scientific community's understanding of cancer-related PN symptoms experienced by female cancer survivors, especially the unique role of BDNF rs6265 polymorphism in these symptoms." (PMID 37462904, 2024). "These insights point to the potential role of the BDNF Val66Met polymorphism as a dual-purpose biomarker, facilitating not only the detection of cancer but also the identification of patients at a heightened risk for ensuing psychological difficulties." (PMID 38988887, 2024). "Increased BDNF expression within tumours has been associated with poorer prognosis in various cancers." (PMID 39684475, 2024). "These contradictory effects and age‐dependent consequences of the BDNF rs6265 polymorphism among cancer survivors were also documented in another systematic review." (PMID 38379321, 2024). "Our current finding provides early evidence of potential sex variations in the influence of BDNF polymorphism on the cancer-related fatigue experience." (PMID 37462904, 2024). "In conclusion, this study suggested potential sex variations in the protective effects of the BDNF rs6265 polymorphism against cancer-related fatigue." (PMID 37462904, 2024). "Numerous studies have established an association between the BDNF Val66Met polymorphism and the incidence of cancer." (PMID 38988887, 2024). "Accordingly, elevated expression of BDNF/TrkB in neoplastic tissue has been linked to poor patients’ prognosis in several cancers." (PMID 39143551, 2024). "Recently, the BDNF has been shown to be overexpressed in various types of cancer and associated with their poor prognosis in promoting tumorigenesis and progression." (PMID 38775506, 2024). "If confirmed, the knowledge of sex variation in the fatigue-protective advantage of the BDNF polymorphism would help advance therapeutic strategies for symptom management to improve health outcomes for cancer survivors." (PMID 37462904, 2024).